IGF1R (insulin like growth factor 1 receptor)
Diseases named in the same sentence as IGF1R in open-access papers (continued):
Sharing a sentence is not in itself a finding about the gene and the disease.
tumor (continued). "It is becoming increasingly evident that the Type-1 insulin-like growth factor (IGF-1R) and its ligands (IGF-1, IGF-2) play roles in both tumor cell proliferation and survival, and proliferation of vascular endothelial cells." (PMID 21197468, 2011). "Using a mouse xenograft model for HNSCC, treatment with antibodies against IGF-1R, EGFR or both receptors resulted in significant differences in median tumor volume." (PMID 21776391, 2011). "After IGF-1 binding to IGF-1R, the signal pathway PI3K/Akt and mTOR are activated to regulate cell proliferation, and are also activated in tumor cells such as acute myeloid leukemia." (PMID 22073238, 2011). "Combination analysis was performed grouping MVP and IGF-1R expression in tumours, showing that all responding patients with low MVP/IGF-1R tumours were free of local disease, relapse or death related disease." (PMID 22040803, 2011). "Male Apcmin/+ mice with an intestinal tumour burden were exposed to a single dose of an inhibitor against EGFR (gefitinib), IGF1R (AZ12253801), 0.5% Tween 80 or combined EGFR/IGF1R inhibitor and culled 4 h post dosing." (PMID 21811251, 2011). "The majority of anti-IGF strategies focused on IGF-1R, the key component of IGF axis that provides mitogenic signal for tumor growth." (PMID 21729319, 2011). "Inhibition of IGF-1R, e.g by monoclonal antibodies against IGF-1R, has been shown to block tumor growth in vitro and in a xenograft model of HCC and to sensitize cells for anti-tumor treatment, indicating that IGF-1R is a promising antineoplastic target." (PMID 21569410, 2011). "A combined therapy targeting IGF1R and EGFR was shown to successfully inhibit tumour cells, which were resistant to IGF1R blockage by overexpressing the EGFR pathway." (PMID 20924377, 2010). "However, aberrations of this molecular pathway such as overexpression of IGF1R, elevated plasma levels of IGF1, loss of IGF2 imprinting, or genetic polymorphisms of the gene encoding IGF1 have been found in many cancers, affecting multiple aspects of malignancy such as tumor growth and metastases." (PMID 21078151, 2010). "Expression of Igf1r and Insr in diverse TME cell types suggests that IGF2 could have paracrine signaling effects that create an immunosuppressive tumor-promoting niche." (PMID 41568176, 2026). "Additionally, tumor growth is enhanced by autocrine and paracrine effects of high local IGF-2 concentrations, which stimulates IGF-1R and IR expressed on tumor cells." (PMID 41179270, 2025). "Functionally, forced IGF1R activation in QBC-939 and RBE cells enhanced proliferation, invasion and orthotopic tumor growth, whereas pharmacologic or genetic blockade produced the opposite phenotype, confirming a causal role for IGF1R in disease aggressiveness." (PMID 41275311, 2025). "In both groups of tumours, no significant variation of cell proliferation after IGF1R knockdown was found." (PMID 40038716, 2025). "Combination therapy targeting FYN +IGF1 R and KDM4 +EGFR synergistically eliminates tumor in vivo." (PMID 40243589, 2025). "Additionally, macrophage-derived IGF-1 activates IGF-1R and PI3K signaling pathways in tumor cells, which promote tumor recurrence following CSF-1R inhibition." (PMID 40076738, 2025). "IGF1R can activate both PI3K and RTK pathways to promote tumor proliferation and invasion." (PMID 39901877, 2025). "In contrast, miRNAs downregulated in rKGAS cells were found to regulate tumor suppressor genes such as IGF1R, TNFAIP3, and MTOR, suggesting that the acquisition of chemoresistance may involve altered regulation of both oncogenic and tumor-suppressive pathways." (PMID 40952575, 2025). "Furthermore, it is observed that the inhibitors against IGF1R or mTOR exhibit suppressive effects on patient-derived tumor xenograft tumors with high IGFRIL expression, through simultaneous blocking of the IGF1R-AKT-mTOR signaling pathway." (PMID 40686314, 2025).
tumor (continued). "At last, in ACC and ACA primary cultures, IGF1R silencing did not affect cell proliferation in either tumour type." (PMID 40038716, 2025). "The IGF1R and IR expression and localisation were investigated by IHC in a cohort of patients with ACC (n = 118), including both primary tumours (n = 107) and local recurrences or distant metastases (n = 11), and ACA (n = 22) and association with clinicopathological features was assessed." (PMID 40038716, 2025). "In tumor tissue, the IGF-1/IGF-1R interaction may be increased, activating intracellular PI3K/AKT and MAPK signaling pathways, increasing proliferation, and causing local depletion of IGF-1." (PMID 41303367, 2025). "HIF1α and HIF2α, through complex mechanisms, synergistically increase IGF1R expression and activate downstream signaling pathways, such as the PI3K/AKT signaling pathway, which promotes tumor cell survival and proliferation, ultimately leading to resistance to temozolomide (TMZ)." (PMID 40290443, 2025). "High IGF1R expression enhances the phosphorylation of PDK1 and AKT, activating the PI3K/AKT signaling pathway, thereby promoting cell proliferation and chemotherapy resistance, exacerbating tumor malignancy." (PMID 40290443, 2025). "Indeed, IGF1R blockade suppressed IGF1R signaling and YAP1 expression in a dose-dependent manner, suppressing tumor cell proliferation, self-renewal, and enhancing survival in orthotopic GBM and BC models." (PMID 41510300, 2025). "IGF1R, the IGF2 receptor, is considered a major therapeutic target due to its role in tumor growth." (PMID 39918792, 2025). "Specifically, the average tumor size was 3,256.5 mm3 in the CpG group, while it was reduced to 1,649.7 mm3 in the TOP2A group (p<0.01), 2,242.5 mm3 in the IGF-1R group, 1,703.2 mm3 in the HIF-1α group (p < 0.05), and down to 361.7 mm3 in the TNBCvax group (p<0.0001)." (PMID 40969744, 2025). "The target mRNAs CDKN1B, TGFR1, and IGF1R showed no significant change between tumor and non-tumor tissue." (PMID 40630212, 2025). "We evaluated the expression of IGF1R and IR isoforms in a panel of four different cell lines: H295R and JIL-2266, derived from ACC primary tumours of female patients, MUC-1 and TVBF-7, derived from ACC distant and perirenal lymph-node metastasis of male patients, respectively." (PMID 40038716, 2025). "Additionally, a biomimetic macrophage membrane-coated nanoparticle featuring a synthetic D-form oligopeptide exhibits a strong affinity for the insulin-like growth factor 1 receptor (IGF1R), which is notably overexpressed on tumor cells." (PMID 40281721, 2025). "In vivo studies also showed similar results; H460 and A549, either over-expressing miR-486 or not, were injected into mice, and the tumor volume and IGF-1R expression levels were significantly lower in mice over-expressing miR-486." (PMID 41153350, 2025). "Moreover, miR-133a-3p can target multiple receptors, such as EGFR, FGFR1, IGF1R, and MET receptors, to inhibit tumor cells." (PMID 40170845, 2025). "For example, IGF1R, PDK4, and SOCS3 are involved in tumor proliferation, migration, and invasion." (PMID 39618816, 2024). "Clinical trials in various cancer patients have failed, with monoclonal antibodies targeting only IGF-1R without IR due to the advancement of tumor growth, most likely arising from the escape mechanism involving insulin." (PMID 39335147, 2024). "Thus, inhibiting this pathway with the IGF-1R inhibitor, linsitinib, limited IGF-1R/AKT signaling and reduced Kitra-SRS tumor growth both in vitro and in vivo." (PMID 38882060, 2024). "In conclusion, circIGF1R acts a tumor suppressor in NSCLC by inhibiting the Wnt pathway through the VANGL2/miR-1270 axis, RBFOX3 promotes circIGF1R biogenesis by binding to IGF1R pre-mRNA, and is induced by paclitaxel to inhibit the migration and invasion of NSCLC cells." (PMID 38191906, 2024).
tumor (continued). "The phosphorylation of IGF-1R activates the phosphatidylinositol 3-kinase/AKT kinase and rapidly accelerated fibrosarcoma kinase/mitogen-activated protein kinase (RAF/MAPK) pathways, leading to tumor progression." (PMID 39238765, 2024). "CCK8 assays revealed that CBX7 and IGF-1R overexpression significantly increased tumor cell proliferation, counteracting the negative impact of FOXC1 knockdown." (PMID 38413558, 2024). "And the inhibition of IGF-1R itself or the downstream signal transduction cascade, namely, the PI3K/AKT/MTOR pathway, exerts potent stimulation on autophagy and other adaptive mechanisms to achieve anti-tumor efficacy." (PMID 38665430, 2024). "Similarly, histological analysis of brain sections obtained from GBM12 tumor-bearing mice demonstrated a significant increase in IGF2 expression and IGF1R phosphorylation co-localized within the region of active rHSVQ replication." (PMID 38853689, 2024). "The compensatory upregulation of molecular target structures, such as EGFR or IGF1R, for example, leads to reduced sensitivity to erlotinib (EGFR inhibitor) or substances targeting the VEGF signaling pathway (IGF1R contributes to tumor angiogenesis through upregulation of VEGF)." (PMID 38730642, 2024). "Additionally, targeting of MET similarly to other RTKs, such as EGFR, IGF1R, and VEGFR, increases tumor cytotoxicity to DDAs." (PMID 38957115, 2024). "We observed that tumor growth was not delayed upon IGF1R abrogation, despite cancer cells maintained IGF1R interference during tumor growth." (PMID 39075581, 2024). "PTK6 may collaborate with a range of growth factor receptors, including as the ERBB family, IGF1R, and MET, as well as a variety of signaling pathways, such as hypoxia, p27/CDK/Cyclins, ERK1/2/P38 to promote tumor progression." (PMID 38573548, 2024). "These may have improved overall anti-cancer efficiency as they can inhibit the tumor-promoting effects mediated by IGF-2 signaling and hybrid IGF-1R/IR receptors." (PMID 39273251, 2024). "In the present study, we observed expression of AXL but not phospho‐IGF‐1R in tumor specimens obtained at both initial biopsy as well as operation in two patients." (PMID 38323355, 2024). "Other docking molecules are recruited to IGF1R when activated, such as SHC domain proteins which are mainly involved in the activation of the BRAF/MAPK and the JAK/STATs signaling pathways, both important regulators of tumor progression and immunomodulation." (PMID 38420122, 2024). "have subsequently demonstrated that co-targeting PD-1 and IGF1R resulted in a significant decrease in the number of T-regs and an increase in intratumoral cytotoxic CD8+ T cells leading to an improvement of anti-tumor efficacy in an in vivo mouse model of lung cancer." (PMID 38420122, 2024). "Two weeks post-tumor injection, mice were randomized into 4 groups (8 mice per group): untreated, treated with anti-PD-1, treated with IGF1R inhibitor (AEW), and treated with a combination of anti-PD-1 and the IGF1R inhibitor (anti-PD-1/IGF1R)." (PMID 39450263, 2024). "For example, a study reported that the NSCLC tumor tissues isolated from smokers showed significantly greater levels of phosphorylated IGF-1R (pIGF-1R) compared with tissues from non-smokers." (PMID 38540176, 2024). "Therefore, our results indicate that activation of the IGF1R pathway is required for EMP acquisition and tumor progression to the aggressive mesenchymal state via ITGAV, priming epithelial cancer cells to TME-derived EMT-promoting signals, such as TGFβ." (PMID 39075581, 2024). "We also demonstrate that activation of insulin-like growth factor-1 receptor (IGF1R) pathway in epithelial cancer cells is necessary to induce EMP and mesenchymal state acquisition in response to tumor microenvironment-derived factors, while promoting ITGAV expression." (PMID 39075581, 2024).
tumor (continued). "In malignant prostate epithelium, IGF1R is induced to recruit to chromatin, directly binding to DNA and interacting with RNA Pol II to upregulate the expression of JUN and FAM21, thus participating in tumor cell survival and migration." (PMID 39404930, 2024). "Disruption of the complex in HNSCC cells in vitro with a peptide mimetic of the organizer site in Sdc1 (called SSTNIGF1R) inactivates IGF1R, even in the presence of IGF1, and relieves the suppression of apoptosis signal-regulating kinase-1 (ASK1), dramatically reducing tumor cell survival." (PMID 36968227, 2023). "A study with GSK1904529A shows that it potently reduces the phosphorylation of both IGF1R and InsR in vitro and in vivo, with no obvious effects on blood glucose levels at doses able to decrease tumor growth significantly." (PMID 37686528, 2023). "In addition, IGF-1R promotes cell proliferation and migration, and changes in cell adherence via MAPK/Ras system all leading to rapid tumor growth." (PMID 37205904, 2023). "Consequently, IR can mediate primary resistance to IGF-1R target therapy, as IR overexpression leads to elevated levels of IR-A, which binds IGF-2 with high affinity, promoting tumor development." (PMID 37834454, 2023). "Additionally, tumor cells expressing elevated levels of the reported CSC markers NRP1, IGF1R, CD44, and PROM1 (CD133) were scattered across several clusters." (PMID 37966117, 2023). "Further evidence of Neu-1′s involvement in IR signaling is that in-vitro and in-vivo studies have concluded that insulin affects tumor progression by acting on the IR and not solely by IGF-1R cross-talk." (PMID 36831374, 2023). "We found that the tumor area had a higher phosphorylation level of IGF-1R (p-IGF-1R) than the adjacent nontumor area." (PMID 36765890, 2023). "In particular, the dual IGF1R/IR inhibitor linsitinib increased tumor cell death and enhanced the antitumor activity of GD2-CAR-T cells, providing a strong indication for the translational development of IGF1R/IR inhibitors as adjuvants for GD2-CAR-T in the future." (PMID 36983330, 2023). "As expected, the level of PYCR1 pY135 and IGF1R phosphorylation were significantly correlated; the signals of PYCR1 pY135 also exhibited a positive relationship with that of HIF-1α in distinct tumor regions." (PMID 37777542, 2023). "Endocrine levels of IGFs or IGFBPs might be predictive for IGF1R targeting, though it seems more likely that IGF tumor expression will have more significant predictive values of response." (PMID 37834331, 2023). "Cumulatively these data suggest that the systemic inhibition of IR/IGF1R has a greater negative effect that any potential effect on tumour size or patient outcome." (PMID 36920947, 2023). "Next, CPL304110 selectivity was analyzed on seven kinases; the results showed that CPL304110 had the highest activity against kinases that share homology with FGFRs (KDR and PDGFRβ) and others that play an important role in tumor development and progression (AURKA, FLT3, IGF1R, JAK2, and TRKA)." (PMID 38282676, 2023). "IGF/IGF-1R mediates cell survival and induces tumor cell invasion and metastasis by crosstalk with the STAT3 signaling pathway, thereby enhancing tumor cell invasion and metastasis, and IGF/IGF-1R can induce cell migration through the PKD or RhoA/PKC signaling pathway." (PMID 36698167, 2023). "In conclusion, our study provides, for the first time, absolute quantification of RTKs in liver tissue from healthy individuals and cancer patients with a focus on CRLM, reflecting a significant suppression of EGFR, INSR, VGFR3, and AXL, and upregulation of IGF1R, EPHA2 and PGFRB in tumour." (PMID 36890818, 2023).
tumor (continued). "Expression of INSR, but not IGF1R, was significantly higher in tumour than in normal gastric tissue." (PMID 34554347, 2022). "FAK interactions with IGF1R and integrins transmit these growth signals by activating effectors, such as PI3K/Akt, promoting glucose consumption to fuel rapid growth of tumor cells." (PMID 36407100, 2022). "In cancers with upregulation of IGF1R and circulating IGF-1 levels, tumor growth may be stimulated by IGF1R activation." (PMID 35597813, 2022). "Consistent with a critical role of IGF-1R in promoting cancer cell proliferation, survival and tumor growth, depletion of PINCH-1 was sufficient to inhibit cancer cell proliferation, survival and tumor growth." (PMID 35401828, 2022). "We thus concluded that tumor cells, especially in the G2 stage, are sensitized for IGF1, IGF2 and Insulin stimulation by increased glucose in the TME, as these growth hormones can activate IGF1R." (PMID 35574343, 2022). "Growing evidence has shown that miR-133a is downregulated and plays tumor suppressor roles in cancer and that it can inhibit proliferation, migration, and invasion of HCC cells by targeting several genes such as IGF-1R, FSCN1, and FOSL2 through the TGF-β/Smad3 signaling pathway." (PMID 35432524, 2022). "Researchers found that deguelin could inhibit the proliferation, invasion, metastasis, and autophagy of tumor cells by regulating many signal pathways (e.g., EGFR/IGF1R-Akt, MAPK, and mTOR)." (PMID 35637651, 2022). "Matrix metalloproteinases (MMPs) regulate remodeling of the extracellular matrix (ECM), which is an important event for metastatic progression of tumor, and some of them also act as IGFBP proteases, ensuring a simultaneous release of IGFs to stimulate IGF1R signaling." (PMID 36013453, 2022). "Given the proven role of IGF/IGF1R in fibroids proliferation, our data suggest that IGF1 may activate ERα in a ligand-independent manner, promoting tumor cell proliferation." (PMID 35884847, 2022). "Moreover, dual inhibition of IGF1R and KRAS signaling (MEK, mTOR and G12C) markedly enhances anti-tumor effects in CRC and NSCLC cells 132-134." (PMID 35966590, 2022). "In TNBC models, BETi JQ1 disrupts enhancer remodeling induced by MEKi trametinib, blocks kinome reprogramming and suppresses tumor growth; in lung cancer models, JQ1 can overcome MEK and TBK1 inhibition resistance via suppressing adaptive activation of YAP1/TAZ and IGF1/IGF1R signaling." (PMID 35966590, 2022). "The activation of the IGF-1/IGF-1R signaling pathway may activate the MAPK and PI3K signaling pathways that are closely related to tumor genesis, resulting in the occurrence of tumor." (PMID 36003786, 2022). "It was also important to see that IGF1R gene expression was higher in the tumor cell line T2 than the nontumorigenic A3 cell line and this one compared to the control cell line." (PMID 36430763, 2022). "Furthermore, tumor xenografts with LINC01291 depletion presented decreased Ki-67 and IGF-1R expression as well as increased cleaved caspase-3 expression." (PMID 33674778, 2022). "Notably, while some of the targets revealed by our analysis (such as IGF1R, HGF, and KAT6A), are well-characterized drivers of tumorigenesis, others are known tumor suppressors e.g., PTEN, EP300." (PMID 35347083, 2022). "Perhaps not surprisingly, the MTB-IGF1R overexpression model showed a similar histological tumor phenotype to the CD8α-IGF1R model." (PMID 35784559, 2022). "Of note, a direct association between IGF1R and AXL pathways is not reported, but tumor cells expressing low AXL levels exhibit high levels of IGF1R phosphorylation." (PMID 36224313, 2022). "By significantly inhibiting IGF-1R activity, PPP was able to decrease pAKT and phosphorylated extracellular signal-regulated kinases 1 and 2 (pERK1/2), induce apoptosis, and lead to complete tumor regression in xenografted and allografted mice." (PMID 36555406, 2022).